WNT3A (Wnt family member 3A)
Diseases named in the same sentence as WNT3A in open-access papers (continued):
Sharing a sentence is not in itself a finding about the gene and the disease.
tumor (continued). "We found that HS20 disturbed the interaction between GPC3 and Wnt3a, blocked Wnt activation, inhibited Wnt3a-induced HCC cell proliferation and showed anti-tumor activity in mice." (PMID 27185050, 2016). "This family has also been shown to be repressed and to suppress (in specific tumour types) a series of oncogenes that include c-Myb, Bmi-1, BCL-2, WNT3A, and Wip1." (PMID 21629246, 2011). "Aberrant expression of VM production-related proteins (MMP2, MMP9, VEGFA, Laminin, Wnt3a, RHOA) as well as immune checkpoint (PD-L1) in tumors and the occurrence of EMT process are considered to be important drivers of VM formation and tumor development as well as metastasis." (PMID 37407689, 2023). "Second, to investigate whether CD44v6 variants are important for β-catenin-MDR1 signaling, we examined the effects of WNT3A and FOLFOX on activation of CD44v6 splicing and β-catenin-MDR1 signaling in oxaliplatin resistant SW480-OXAR/SQ tumor cells." (PMID 35982950, 2022). "Importantly, sICAM‐1 recruits macrophages to the tumor microenvironment, and tumor‐educated macrophages produce wingless‐type MMTV integration site family, member 3A (WNT3A) for the mesenchymal shift of GBM." (PMID 34813169, 2022). "Tumor organoids were grown without Wnt‐3a conditioned medium to eliminate normal colon cell contamination in tumor tissues." (PMID 34850547, 2022). "Note that because normal human colon epithelial organoids require Wnt ligand (Wnt 3a) in the culture medium, it was considered that organoids cultured in Wnt3a-free media were CRCOs and further characterization relative to the primary tumor was not undertaken." (PMID 35425715, 2022). "Furthermore, WNT3A signaling activity is increased in the CD44v6(+)CIC population isolated from SW480-5FUR, SW480-OXAR and SW480-FR SQ tumor cells overexpressing WNT3A, as analyzed by FACS." (PMID 35982950, 2022). "Tumor-derived 3D cultures grown in the presence of Wnt3A-CM were treated or not with N6L 30 μM for 24 h." (PMID 34203710, 2021). "Additionally, WNT3A and WNT5A protein levels in tumor mouce xenografts of two groups were analyzed by immunohistochemistry." (PMID 34093821, 2021). "Tumor-derived 3D culture with Wnt3A-CM, but not treated with N6L (control), showed high immunostaining for active β-catenin." (PMID 34203710, 2021). "Briefly, normal PDCOs were grown in medium added with the Wnt3a factor (+W), whereas tumor PDCOs in medium in the presence or absence of the Wnt3a factor (+W or -W, respectively)." (PMID 34154611, 2021). "Moreover, miR-128 overexpression significantly inhibited proliferation, EMT process and tumor growth by directly targeting GSPT1 and WNT3A." (PMID 32127947, 2020). "Through inducing WNT3A secretion, LINC00662 activated Wnt/β‐catenin signaling in HCC cells in an autocrine manner and further promoted HCC cell proliferation, cell cycle, and tumor cell invasion, while repressing HCC cell apoptosis." (PMID 31785055, 2020). "WNT3a conditioned medium has no substantial effect on the growth of tumour cell clones under adherent conditions but significantly stimulates the proliferation in soft agar conditions although this response does vary between tumour cell clones." (PMID 30926782, 2019). "Notably, the incidence of serum Wnt3a was 81.4% in HCC patients with AFP level less than 20 μg/L (48/59), 92.6% in the cases with tumor size less than 3.0 cm (75/81), and up to 93.9% when Wnt3a plus AFP combination." (PMID 31737122, 2019). "Functionally, silencing Wnt3a by Crispr/Cas9 suppressed the proliferation, colony formation, induced cell cycle arrest of HCC cells by de-activating Wnt/β-catenin pathway in vitro, and inhibited xenograft tumor growth in vivo." (PMID 31737122, 2019).
tumor (continued). "In addition, blocking Wnt3a antibody, administered in vivo, increases expression of the activation marker OX40L in tumor-infiltrating DCs44." (PMID 30926812, 2019). "As expected, tumor organoids grew in the absence of Wnt3A (Wingless-Type mouse mammary tumor virus integration site family 3A), R-Spondin, and nicotinamide." (PMID 31752287, 2019). "Furthermore, the impact of WNT3A, FH535, XAV939, or ß-catenin siRNA on the differentiation status of the RMS tumor cell lines was analyzed by qRT-PCR." (PMID 30568936, 2018). "To determine the expression of Wnts in non-CRC cell types in the tumor grafts, we sorted host-derived endothelial cells, fibroblasts, macrophages and dendritic cells and tested mRNA levels of Wnt3, Wnt3a, Wnt5a and Wnt10a in these cells." (PMID 28147310, 2017). "Antral organoids of Mist1-CreERT; Apcflox/flox mice can grow without Wnt3a and R-spondin 1 in culture media only when recombination is induced by tamoxifen, suggesting that the tumor development in these mice is cell-autonomous effect." (PMID 29340033, 2017). "Accordingly, in vitro studies have shown that tumor-derived TGFβ is able to induce activation of human prostate stroma through heavy deregulation of key signalling pathways crucially involved in maintaining tumor-promoting features, including FGF2, CTGF, SDF1, WNT3A and IGF axes." (PMID 26375444, 2015). "Alteration of the miR-15a and miR-16-1 translates into multiple tumor-promoting processes through the derepression of key cell cycle-and apoptosis-related genes such as B-cell CLL/lymphoma 2 (BCL2), wingless-type MMTV integration site family-member 3A (WNT3A) and cyclin D1 (CCND1)." (PMID 25309903, 2014). "Wnt expression at the metastatic site was rare if the primary tumor tested negative for both wnt3a and wnt5a." (PMID 24564183, 2014). "In summary, by co-expressing HCV core protein and Wnt3A in hepatocytes and HCC cell lines, we have found that the HCV core protein can potentiate and synergize with Wnt/β-catenin signaling pathway in promoting cell proliferation and tumor growth." (PMID 22110662, 2011). "In addition to Wnt3A and Wnt1, upregulation of Wnt3A, Wnt4, Wnt5A, and Wnt10B has also been observed in both tumor tissue and the adjacent non-tumorous liver." (PMID 40943055, 2025). "- miR-766-3p acts as tumor suppressor miRNA in HCC, maybe by targeting the Wnt3a/PRC1 pathway." (PMID 37205191, 2023). "For example, activity changes in oncogenic pathways often modulate the tumor microenvironment, and we observed a strong correlation between promoter or enhancer methylation and target gene expression for the MAPK pathway (EGFR) and WNT-beta-catenin pathways (CTNNB1, WNT3A and WNT7B)." (PMID 34987166, 2022). "Given that CAFs derived from resistant tumor cells (PD-5FUR, PD-OXAR and PD-FR CAFs) also express significant levels of CD44v6 compared to its absence in normal-fibroblasts, we determined if CD44v6 induces WNT3A activation in CAFs since it regulates WNT3A/β-catenin signaling in CICs." (PMID 35982950, 2022). "Next, the relative expression of ß-catenin and Wnt3a mRNA and protein expression was also determined and we found a significantly lower β-catenin, and Wnt3a, mRNA and protein expression among the sh-SNHG9 group tumor tissue relative to the sh-NC group mice tumor tissue." (PMID 34539877, 2021). "To determine the mechanism of WP action in the biology of ID-MA tumor cell phenotypes in this study, we used attenuators of WP signals including WntC59 and XAV939, beta-catenin siRNA, sulindac sulfide as well as stimulators of WP signals including Wnt3A recombinant protein and LWnt3ACM." (PMID 27902969, 2017). "However, the Wnt3a transduced into HCC cells may promote cell cycle progression and accelerate tumor formation in athymic nude mice." (PMID 26369691, 2015).
tumor (continued). "In a dose–response analysis of Mock/LM cells with or without Wnt3a treatment (102–104 cells injected per mouse), no tumor growth was evident at 4 weeks in the 102 cell mice; 3 of 6 mice from the 103 cell group had tumors and all 6 of the 104 cell mice developed tumors." (PMID 26075748, 2015). "Wnt3a expression was not significantly correlated with gender, age, and tumor size." (PMID 25499541, 2014). "To uncover the mechanism of HOXB3 driving tumor progression, we performed RNA-sequencing in HOXB3 negative (HOXB3-) and HOXB3 high (HOXB3 + ) staining CRPC tumors and determined that HOXB3 activation was associated with the expression of WNT3A and enriched WNT pathway genes." (PMID 36973255, 2023). "Interestingly, WNT3A increases STI1/HOP expression in GBM cells, suggesting that WNT signaling could regulate CMA, or that GBM cells take advantage of increased STI1/HOP expression to sustain tumor growth and modulate GSCs." (PMID 33312955, 2020). "Interestingly, the tumour organoids were capable of growing and resulted in an increase in the number of buds/lobes from their original cystic shape bodies in a growth medium without Wnt-3A." (PMID 29535828, 2018). "Overall, our studies demonstrated that DKK4 inhibits tumor metastasis in CRC and uncovered a novel regulatory mechanism through the Wnt3a/DKK4/AKT/s552 β-catenin negative feedback loop in CRC." (PMID 36181792, 2022). "Tumor-derived 3D culture derived from MIA PaCa-2 tumors and culture in the absence of Wnt3A grew slower and mostly formed small irregular masses of cells (Wnt3A, arrows)." (PMID 34203710, 2021). "While several studies found that Wnt3a-conditioned medium, recombinant Wnt3a or GSK3 inhibition enhanced proliferation of HMCLs, others did not observe this positive effect on tumor growth." (PMID 30770859, 2019). "The tumor sphere formation assay and cell viability assay showed that LASS2 overexpression effectively sensitizes BCSCs to cisplatin, but it was not fully effective in BCSCs treated with Wnt3a." (PMID 38191448, 2024).
cancer (136 papers, 2008 to 2025). A tumor composed of atypical neoplastic, often pleomorphic cells that invade other tissues. "Wnt3a and Sema4C mediate mechanical hyperalgesia in contexts of cancer-associated or inflammatory pain respectively." (PMID 36231105, 2022). "It has been found that Wnt activation was greatest at the boundary between epithelial and stromal compartments, and both cancer cells and cancer-associated fibroblasts mediated reciprocal stimulation by paracrine signals, mainly WNT-3A." (PMID 32183420, 2020). "The prediction that the only Wnt capable of binding to SMO with at least moderate affinity is Wnt3a is quite interesting, considering that both of these proteins are implicated in numerous cancer types, albeit studied in distinct signalling contexts." (PMID 31454915, 2019). "Increased WNT3A expression has been reported in association with clinical stage, malignant behavior in several cancers." (PMID 27852072, 2016). "In addition, reports from the literature already established the association of Wnt-3a with GPCs in several different types of cancers." (PMID 33947326, 2021). "Interestingly, TIRY in CAFs suppressed exosomal delivery of miR-14 to neighboring cancer cells, which caused the upregulation of WNT3A, a miR-14 target, and activation of Wnt/β-catenin signaling in cancer cells." (PMID 33050576, 2020). "All these evidence clearly reveals that Wnt3a is a potential cancer metastasis-associated protein." (PMID 31528227, 2019). "Yet another mode may be Wnt3a promoting a cancer-associated fibroblasts-like phenotype in fibroblasts, partially through the TGF-β/Smad2 signaling activation by a β-catenin-dependent mechanism, indicating that Wnt and TGF-β signaling are linked by Smad." (PMID 24427302, 2014). "A recent study indicated that upregulated LINC00662 contributed to secretion of WNT3A from cancer cells and activation of Wnt/β-catenin pathway in macrophages via paracrine manner, promotion of macrophages polarization to M2 type, causing worse prognosis of patients with cancer." (PMID 33148302, 2020). "Wnt3A, a potent activator of Wnt/β-catenin signaling, is involved in the progression of many cancers." (PMID 40657359, 2025). "Their dysregulation contributes to cancer, with alternative Wnt signaling pathways (Wnt5a/b and Wnt3a) activating YAP/TAZ independently of canonical β-catenin signaling." (PMID 39851951, 2025). "Cancer cells release Wnt3a, which activates the Wnt/β-catenin signaling pathway in cancer-associated fibroblasts (CAFs)." (PMID 40230452, 2025). "Despite reports of methods that selectively inhibit the growth of normal organoids by removing niche factors and allowing only cancer organoids to proliferate, we used culture media containing Wnt3a and RSPO." (PMID 39688793, 2025). "This dose of Wnt3A has been used in multiple studies for in vitro treatment in both normal and cancer cells." (PMID 39028933, 2024). "In in vitro studies on MDA-MB-231 cancer stem cells, TQ inhibited Wnt3a and PI3K and blunted the stimulatory effects of VEGF, EGF, and FGF." (PMID 38468988, 2024). "In in vitro studies on MDA-MB-231 cancer stem cells, TQ inhibited Wnt3a and phosphatidylinositol-3 kinase (PI3K) and blunted the stimulatory effects of VEGF, EGF, and FGF." (PMID 38468988, 2024). "Cryptolepine had no obvious effects on MMP2 and MMP9 expression in unstimulated cells but significantly reduced WNT3a-induced expression of these genes, confirming the selectivity of cryptolepine for cancer cells with hyperactive WNT signaling." (PMID 37513937, 2023). "In contrast to the SNU475 and HUH7 cells, Wnt3a treatment mostly mitigated the cancer effect by reversing the differential regulation of lipids in Hep3B cells (113 lipids represented in green bars)." (PMID 37699867, 2023). "In conclusion, these results indicate that ASPM contributes to the cancer progression of RCC by targeting the Wnt3a signaling pathway." (PMID 37928425, 2023).
cancer (continued). "The ZINC06804365 has been tested and reported as a potential inhibit for many signaling pathways such as Wnt-3a and also as having inhibitory activity against the Tankyrase-2 enzyme which reportedly has anti-cancer activities." (PMID 36551744, 2022). "In the current study, it also became evident that, at the supramolecular level changes in collagen in cancer-invaded ECM, there was an association, direct or indirect, with WNT1, WNT3A, and WNT5A signaling." (PMID 36452484, 2022). "Wnt-3A is widely used for many types of cancer organoids and can be replaced by a Wnt-3A conditioned medium." (PMID 35856555, 2022). "Wnt3a, as one of Wnt family members, plays a critical role in initiation, progression, invasion and metastasis of cancer." (PMID 35419295, 2022). "WNT3A regulates cancer cell stemness and increases metastatic potential via CTNNB1 signaling pathway and upregulation of Notch3 31,32." (PMID 34093821, 2021). "Collectively, these data provided evidence that GOLPH3 interacts with CKAP4 to enhance the secretion of exosomal WNT3A, thereby inducing metastasis and the cancer stem cell-like phenotype in NSCLC." (PMID 34671013, 2021). "The co-immunoprecipitation assay revealed increased levels of binding between Wnt-3a and glypicans in cancer cells, suggesting a relationship between these proteoglycans in this pathway." (PMID 33947326, 2021). "Taken together, our results indicated that GOLPH3 promotes the secretion of exosomal WNT3A to enhance metastasis and the cancer stem cell-like phenotype of NSCLC cells." (PMID 34671013, 2021). "WNT3A and WNT5A were proteins have been implicated in several biological processes, including regulation of cell fate and cancer proliferation." (PMID 34093821, 2021). "In this study, we found that the GOLPH3-transduced cell exosomes treatment enhanced the cancer stem cell-like phenotype and cancer metastasis more effectively than treatment with recombinant WNT3A." (PMID 34671013, 2021). "As the strongest Wnt/β-catenin stimulator, Wnt3a has been proposed to participate in numerous cancers." (PMID 34456337, 2021). "Previously, EV-mediated transfer of Wnt 11, Wnt3a, Wnt5b, and Wnt4 has been described in the progression of various cancers." (PMID 33234148, 2020). "Few biological inducers of this process produced by cancer cells have been reported so far, one of such factors being Wnt3a." (PMID 32819314, 2020). "As classic signaling molecules, EV-shuttled Wnt signaling molecules, such as Wnt 11, Wnt3a, Wnt5b, and Wnt4, have been reported to be involved in cancer progression." (PMID 33234148, 2020). "Although we saw a growth suppression role for stromal-derived SULF1 in the context of Wnt3A signaling, it is possible that signal transduction of other cancer-promoting pathways are concomitantly potentiated." (PMID 32413029, 2020). "The signaling of Wnt3a at the cancer cell surface is facilitated by heparan sulfate on other proteoglycans, such as syndecan or glypican, acting as signaling co-receptors." (PMID 32413029, 2020). "PRC1 in HCC tissue is regulated by Wnt3a signaling, exerting an oncogenic effect by promoting cancer proliferation, stemness, metastasis, and tumorigenesis; high expression of PRC1 was associated with early HCC recurrence and poor patient outcome." (PMID 31001331, 2019). "FZD8, plasminogen activator, urokinase receptor, ITGA2, WNT2B, TIMP3, WNT5B, FGF5, heparanase, HBEGF and WNT3A were up-regulated in the proteoglycan pathways in cancer, whereas WNT10A, PIK3R3, IGF2 were down-regulated." (PMID 30482199, 2018). "Accumulating evidence has suggested Wnt-3a, one of Wnt family members, plays pivotal roles in regulating cell growth via the canonical Wnt signaling pathway in various types of cancer." (PMID 29843798, 2018). "Predictably, the drug combinations cooperatively blocked constitutive and Wnt3a-induced SOX4 expressions in cancer cell lines, and this effect was rescued in DDIT3−/− cells." (PMID 29977599, 2018).